TNF (tumor necrosis factor)
Diseases named in the same sentence as TNF in open-access papers (continued):
Sharing a sentence is not in itself a finding about the gene and the disease.
tumor (continued). "NK cells can initiate anti-tumor responses through directly killing tumor cells, secreting cytokines, including IFN-γ and TNF-α, and recruiting other anti-tumor immune cells." (PMID 33995371, 2021). "LPS can activate toll-like receptor (TLR) 4, produce proinflammatory cytokines (tumor necrosis factor-α [TNF-α], interleukin [IL]-6 and IL-1), and contribute to injury and inflammation-driven tumor promotion." (PMID 34206200, 2021). "This review summarizes a new gene family, tumor necrosis factor-α (TNF-α)-inducing protein (tipα), which is secreted by H. pylori and acts as a tumor promoter." (PMID 33804551, 2021). "In tumor environment, it has been reported that AST decreased the amount of inflammatory markers such as TNF-α, IL-6, and IFNγ via NFk-B inhibition." (PMID 33509300, 2021). "CTLs can not only utilize perforin-granzyme pathway and death ligand to mediate tumor cell apoptosis, but can also secret a series of cytokines, such as IFN-γ and TNF-α, to exert direct cytotoxicity or interact with other immune cells." (PMID 34217349, 2021). "Anti-TNF-α treatments can facilitate cell death and reduce the expression levels of pro-inflammatory cytokines to attenuate HCC tumor progression." (PMID 34948424, 2021). "This revealed an expansion of these tumor-specific CD8+ T cells, producing the cytokines IFN-γ and TNF-α in the treated mice, compared to control (untreated) mice, in which the NPs played the largest role." (PMID 34575546, 2021). "TNFα increases TRAIL expression in mesenchymal stem cells (MSCs), inhibiting tumor growth by apoptosis induction of cancer cells." (PMID 34371753, 2021). "Here, we also demonstrated that propolis decreased the levels of proinflammatory mediators, including TNF-α, IL-1β, and IL-6, as well as NLRP3 inflammasome to improve the tumor inflammatory microenvironment." (PMID 33628847, 2021). "When stimulated by inflammatory cytokines (IL-1, TNF alpha, and PDGF), the KCs and HSCs secrete abundant osteopontins, which play a key role in many cell-signaling pathways that promote inflammation, tumor growth, and metastasis." (PMID 34947886, 2021). "First, in the primary tumor site, primary tumor cells secrete soluble growth factors (as VEGF-a, TGF-b and tumor necrosis factor alpha) and EVs (see section 4.1) containing miRNAs, integrins, growth factor receptors, and chemoattractants." (PMID 34446834, 2021). "Some cytokines/chemokines such as TNF-α, IL-18, and RANTES have been reported to be directly involved in tumor growth via the stimulation of their receptors expressed on the tumor cells." (PMID 34436224, 2021). "As a part of the tumor microenvironment, oxidative stress such as ROS could up-regulate γ-GT via the redox regulation of many genes, Moreover, inflammatory cytokines such as interferon-α/β and tumor necrosis factor α could also stimulate the expression of γ-GT." (PMID 34663242, 2021). "Tipα induces strong expression of TNF-α, IL-8, IL-1, and chemokines and promotes EMT and tumor development in cells via mechanisms different from those of CagA and VacA." (PMID 33804551, 2021). "These genes were mainly involved in tumor proliferation and immune response-related biological processes/molecular functions and signaling pathways, such as MAPK, TNF, and IL-17." (PMID 34804923, 2021). "This review also highlights the inflammatory (pro- or anti-) roles of different cytokines (ILs, TGF-β, and TNF-α) and chemokine (CC, CXC, C, and CX3C) families in the lung TME, provoking tumour growth and subsequent metastasis." (PMID 34336101, 2021). "Among them, Th1 cells, characterized by production of IFNγ and TNFα, can optimize CTL activity, and thus promote anti-tumor immunity." (PMID 34794428, 2021). "The administration of mimic MiR-124 also possesses an anti-tumour effect, and hence, miR-124 increases the level of INF-y, IL-2, and TNF-α." (PMID 34885253, 2021).
tumor (continued). "Some cytokines that are involved in inflammation response, including IL‐1β, IL‐6, TNF, and C‐reactive protein (CRP), are increased in depressed patients and promote tumor progression." (PMID 34723436, 2021). "By fusing the N terminus of human tumor necrosis factor (TNF)-α with CNGRCG, a protein called NGR-hTNF was generated and was able to recognize CD13 and increase leakage from the vasculature to tumor tissue, resulting in an enhancement in antitumor effects." (PMID 33957995, 2021). "CRISPR/Cas9-mediated editing of A2AR rendered CAR T cells resistant to NECA in terms of their capacity to secrete IFNγ, TNF, and MIP1α (CCL3) upon coculture with either OVCAR-3 cells or MCF7 cells, another Lewis Y+ tumor cell line." (PMID 34050151, 2021). "Virus infection and tumour microenvironments induce type I IFN, IFN‐γ, and tumour necrosis factor α (TNF‐α) production, which in turn promotes the induction of immunoproteasomes and components of the PLC." (PMID 34310018, 2021). "These TAMs secrete a number of factors, including interleukin-1 (IL-1) and tumor necrosis factor-α (TNF-α), which have been shown to promote tumor invasion and metastasis." (PMID 34722553, 2021). "The TNF-α involvement in the development of cancer is complex, and the balance between the high and low levels of TNF has an adverse effect on tumor growth." (PMID 34379689, 2021). "In CRC, EMT is further accelerated by TNFα‐secreting macrophages, inducing p38 MAPK signaling in tumor organoids." (PMID 34459003, 2021). "When given prophylactically, anti-PD1 treatment led to an increase in the incidence of NASH–HCC and in the number and size of tumour nodules, which correlated with increased hepatic CD8+PD1+CXCR6+, TOX+, and TNF+ T cells." (PMID 33762733, 2021). "Compared with the control, we found that the expression of extrinsic protein TNF-α increased and the expression of internal protein Bcl-2 decreased in ICT-treated tumor tissues." (PMID 33460401, 2021). "The enhanced cytolytic activity and the increased serum IFN-γ and TNF-α concentration in vitro, as well as the increased serum IFN-γ concentration in vivo indicated that miR155 co-expression improved the anti-tumor function of anti-CD19 CAR-T cells." (PMID 35046962, 2021). "Interferon-γ (INF-γ), tumor necrosis factor-α (TNF-α), transforming growth factor-β (TGF-β), and interleukin (IL)-1, −2, −6, −10, −17 are predominant present in tumor microenvironment and represent different type of these cytokines." (PMID 34759748, 2021). "LAG3 is a molecule involved in blocking tumor cell proliferation and regulating the production of IFN-γ and TNFα cytokines." (PMID 34575678, 2021). "Many researchers have observed that tumor development pro-angiogenic factors, such as VEGF, basic and acidic fibroblast growth factor, tumor necrosis factor-α, and interleukin-1 are enhanced in multiple pathological processes." (PMID 33850225, 2021). "This leads to diminished cytotoxic killing activity against tumor cells and a decreased secretion of in anti-tumor cytokines such as IFN-γ and TNF-α." (PMID 34960142, 2021). "This T lymphocyte population mediates anti-tumor activity through antigen-specific cytotoxicity and by producing anti-tumor cytokines, namely IFN-γ and TNF-α." (PMID 34440038, 2021). "And in tumor microenvironment, the interaction between PD-L1 and PD-1 can inhibit IFN-γ, TNF-α and granzyme B secretion in T cells." (PMID 34522232, 2021). "Specifically, we show that a 3-PRE promoter composed from PREs responding to IFNγ, TNFα, and hypoxic stimuli can be employed to restrict CAR expression to the tumor site." (PMID 33514819, 2021). "The impact of C-7 on the levels of various cytokines (IFNγ, TNF, IL-6, and IL-10) and the chemokine CXCL10 was assessed in 1-day co-culture supernatants of dissociated CRC tumor cells and autologous PBMC." (PMID 34771609, 2021).
tumor (continued). "We observed significant changes in tumorigenesis-related markers including CD133, Bmi-1, VEGF, MMP-3, IL-1β, IL-6, TNF-α, and MDR in the tumor group compared with the control group." (PMID 34527741, 2021). "As an inflammatory factor, TNF-α is a major immunomodulatory and proinflammatory factor and TNF-α would enhance the adhesive capacity of peritoneal mesothelial cells and promote tumor cell adhesion." (PMID 34641334, 2021). "IL1A is one of the prominent inflammatory cytokines and contributes to tumor invasion, angiogenesis, and metastasis by inducing VEGF, TNF-α, HGF, and TGF-β." (PMID 34203721, 2021). "After 24-h co-incubation of tumor cells and effector T cells at an E:T ratio of 10:1, B7-H3 CAR-T cells produced significantly higher amounts of IFN-γ, TNF-α, IL-2, IL-6, IL-4 and IL-10 in the culture supernatants compared with vehicle T cells." (PMID 33514401, 2021). "For instance, TNF‒TNFR2 interaction on breast cancer cells promotes highly suppressive phenotypes of regulatory T-cells and, thereby, enhances tumor escape from immune surveillance." (PMID 33917839, 2021). "We therefore assessed the production of several effector molecules important for T cell mediated tumor immunity (IFN-γ, GrB, IL-2, IL-17, IL-22, TNF) following polyclonal stimulation with PMA and Ionomycin." (PMID 33885944, 2021). "It is well known that cytotoxic CD8+ T lymphocytes are crucial components of tumor-specific cellular adaptive immunity, and they produce perforin, granzyme, or TNF, IFN-γ to kill tumor cells or induce apoptosis." (PMID 33882892, 2021). "WAT hypoxia upregulates the secretion of proinflammatory cytokines, namely tumor necrosis factor (TNF)-α, interleukin (IL)-1β, IL-6, and monocyte chemoattractant protein (MCP)-1, providing a tumor-permissive niche for transformed infiltrating cells." (PMID 33922898, 2021). "ANG-2, secreted from tumor and vasculature cells, can enhance IL-10 and mannose receptor expression, while decreasing that of TNF-α and IL-12, thereby weakening TAM anti-tumor activity under hypoxic conditions." (PMID 34603327, 2021). "In a murine model, TNF-α, IFN-γ, IL-1, and IL-10 were demonstrated to increase significantly after a cycle of cryoablation of tumor tissue in an experimental setting." (PMID 34830949, 2021). "Our findings suggest that Lnc-PCIR promotes tumor growth and metastasis via up-regulating the mRNA/protein level of TAB3 and PABPC4, activating TNF-α/NF-κB signaling pathway in TNBC." (PMID 34012913, 2021). "Similar to CD95L, TNF-α and/or TRAIL are also expressed in tumor cells of different origins, including PDAC." (PMID 34771621, 2021). "The resulting hyperactivation of inflammatory mediators, including TNFα, TGF-β, interleukins, and prostaglandins can contribute to the development of neoplasia." (PMID 34885171, 2021). "The upgraded levels of TNF-α and IFN-γ in the tumor tissue indicated the activation of antitumor immune responses by 5ApCB treatment." (PMID 34782610, 2021). "This outcome is different from the anti-vascular effect of TNFα, where TNFα-targeted peptides bind to tumour blood vessels or ECM proteins that are primarily located around tumour blood vessels." (PMID 34683956, 2021). "When MUC1-negative tumour cells (A431)were used as the stimulator, MUC1-specific CAR-T cellsshowed no significant secretion of IL-2 (30 ± 2.82 pg/mL, 1-fold), TNF alpha (8 ± 2.82 pg/mL, 1.7-fold) and IFN-γ (22 ± 2.82 pg/mL, 1.2-fold)." (PMID 32347044, 2021). "Secondly, we developed a new biologic agent, TNFα-CSG, which is an immune-modulating cytokine that binds specifically to tumour ECM." (PMID 34683956, 2021). "While most studies suggest that diverse NKT cells inhibit anti-tumour immunity, iNKT cells contribute to natural tumour surveillance with immediate cytokine secretion (IFN-γ, TNF, IL-13, IL-17, IL-4, IL21, IL-22) and FasL/TRAIL pathways." (PMID 33499101, 2021).
tumor (continued). "Irradiated BM-MSC1 secretes a large amount of TNF-α and IFN-γ, which: (i) inhibit the proliferation of tumor cells by deregulating Wnt and TGF-β/Smad signaling and (ii) induce the apoptosis of tumor cells by blocking their cell cycle in the G1 phase." (PMID 34830312, 2021). "Due to the increased expression of tumor necrosis factor‐alpha (TNF‐α) and intercellular adhesion molecule 1 (ICAM‐1), N1 (anti‐tumor) phenotype neutrophils are cytotoxic toward tumor cells." (PMID 34390218, 2021). "On the other hand, pro-inflammatory cytokines released by immune effector cells, such as IFN-γ, IL-6, TNF-α, IL-1 and TGF-β, up-regulated IDO-1 on tumor cells, thus representing an immune escape mechanism." (PMID 33920505, 2021). "However, TNF exerts many of its actions through TNF receptor 1 (TNFR1) which upregulates downstream pro-inflammatory pathways such as NF-κB, AP-1, IL-8, vascular endothelial growth factor (VEGF), and matrix metalloproteinases (MMPs) implicated in tumour survival, angiogenesis, and migration." (PMID 34944729, 2021). "Immune modulating cytokines (TGF-β, IL-10, IL-17, and IL-23) facilitate tumor development, while others (IFN-γ, TNF-α, GM-CSF, IL-2, IL-6, IL-17, and IL-12) promote immune surveillance and delay its growth." (PMID 34518597, 2021). "In the 4T1 tumor and B16 melanoma models, not only the production of IgG and the secretion of cytokines, such as IFN-γ, interleukin-4 (IL-4), and TNF-α, were upregulated; the effector T cell CD8+ was activated, and the number of Tregs was reduced." (PMID 34842684, 2021). "IN_in_r1 induces a preferable profile of immune response rich in IFN-γ/TNF-α/IL-2 and IFN-γ/IL-2/GrB producing CD8+ T cells, and IFN-γ/TNF-α and IFN-γ/IL-2/TNF-α producing CD4+ T cells, allowing better control of tumor cell challenge." (PMID 34199989, 2021). "We also found that Poly6 treatment increased the production of TNF-α or IFN-γ producing CD4 and CD8 T cells in tumor tissue, which have anticancer effector functions." (PMID 33499256, 2021). "At the same time, the DC boost approach reinforced migratory dermal DC subsets to prime gp100-specific CD8+ T cells in tumor-draining LNs that expressed PD-1/TIM-3 and produced interferon γ (IFNγ)/tumor necrosis factor α (TNFα)." (PMID 33408092, 2021). "CD8 T lymphocytes are able to exert their anti-tumour cytotoxic effects via the secretion of TNFα and IFNγ leading to the apoptosis of tumour cells, when the T-cell receptor (TCR) binds its cognate peptide:MHC antigen expressed on tumour cells." (PMID 33995362, 2021). "Previous works also indicated that metastatic melanoma cells secrete a large amount of TNF-α, IL-6, IL-12, IFN-γ, VEGF, eotaxin, and RANTES, triggering a cascade of effects that include the increase of MMP-2 enzymatic activity and tumor cell aggressiveness." (PMID 33466236, 2021). "The NK-exosome-treated tumor group showed a meaningful reduction in the expression of Bmi-1, MMP-3, IL-1β, IL-6, TNF-α, Bax, and Bcl-xL compared with the tumor group." (PMID 34527741, 2021). "Increased in vivo efficacy by A2AR-knockdown CAR T cells was associated with increased expression of effector-related genes in tumor-infiltrating CD8+NGFR+ CAR T cells such as IFNγ, TNF, IRF4, and Granzyme B." (PMID 34050151, 2021). "Despite their potent effects on certain cell lines as a single agent due to the presence of endogenous TNF-α, SMAC mimetics are ineffective as a monotherapy in most tumor cell lines." (PMID 34298601, 2021). "eEF-2K increases tumor necrosis factor-alpha (TNF-α), promotes TAM survival and function, induces nitric oxide (NO) in activated macrophages, and contributes to aggressive tumor behaviors." (PMID 35010954, 2021). "To illustrate, while M2b polarized macrophage conditioned medium stimulates tumor cell proliferation and IDO1 expression in vitro, this is reduced upon TNFα neutralization." (PMID 34445397, 2021).
tumor (continued). "Depending upon their microenvironment, TAMs mainly polarize toward “M1”, which secret TNF‐α, IL‐12, and promote antitumor resistance, or “M2” phenotype that secret IL‐10, TGF‐β, and play vital roles in angiogenesis and tumor progression." (PMID 34423566, 2021). "In SMMC-7721-tumor-bearing mice, Tf-LP-ERN treatment increased the serum concentration of TNF-α (P < 0.01) and decreased the serum concentrations of IL-10 (P < 0.05) and CCL11 (P < 0.05)." (PMID 34513705, 2021). "Our in vitro and in vivo data consistently indicate that CDX2 induces the migration and infiltration of NK cells, increases the secretion of IFN‐γ and TNF‐α by NK cells, enhances NK cell toxicity against HNSCC, and suppresses the tumour growth in mice." (PMID 33733587, 2021). "Administration of SL7207 is accompanied by a change in the immune phenotype of the tumor‐infiltrating cells toward pro‐inflammatory, with expression of the TH1 cytokines IFN‐γ, TNF‐α, and IL‐12 significantly increased." (PMID 34633664, 2021). "presence of infiltrating B cells correlated with increased tumor aggressiveness and reduced disease-free survival in human HCC.CD20+B cells that produce TNF-α limit senescence, which is beneficial to the progress of HCC." (PMID 34235074, 2021). "The increased levels of several pro-inflammatory cytokines like TNF-α, IL-8, IL-10, and growth factors like TGF-β have been observed in the tumor microenvironment." (PMID 33926547, 2021). "Subsequently, the secretion of TNFα and CCL19 induces the infiltration and maturation of DCs in tumor tissues, thus inhibiting NSCLC progression." (PMID 34660305, 2021). "Meanwhile, Met@Man-MPs treatment markedly increased the levels of pro-inflammation cytokines IFN-γ, TNF-α, and IL12p70, while decreased the levels of anti-inflammation cytokine TGF-β in tumor tissues." (PMID 33469052, 2021). "In this study, we focused on the metabolic effect of neutrophils on BC cells and identified IL1β and TNFα as a vital bridge that connected C5RN and tumor cells." (PMID 34312368, 2021). "The TNFRSF21 is a member of the TNF/TNFR family and plays a critical role in pathogen recognition, immune response, inflammation, and tumor progression." (PMID 34449805, 2021). "We therefore checked the protein expression of MAFbx and MuRF1 in the TNF-α-induced myotube atrophy model and the CT26 tumor-bearing mice to confirm the anti-catabolic effects of L-carnitine." (PMID 34724970, 2021). "NF-κB also regulates the expression of tumor necrosis factor (TNF) and cyclooxygenase 2 (COX-2), which are overexpressed in an inflammatory CRC microenvironment and are involved in tumor growth promotion." (PMID 34113338, 2021). "Consistent with increased tumor-infiltrating lymphocytes (TILs) in tumors, CA170 plus KVax treatment also increased the expression of IFN-γ, TNFα, and granzyme B in tumor-infiltrating CD4+ and CD8+ T cells in tumors." (PMID 34302042, 2021). "Accordingly, serum levels of anti-tumorigenic cytokines (TNF-α and IL-17) were decreased and the serum concentration of immunosuppressive IL-10 was increased in MSC-treated tumor-bearing animals." (PMID 34830312, 2021). "Some TI B cells enhance antitumor immunity by producing tumor-specific antibodies, presenting tumor-specific antigens, and secreting cytokines (IFN-γ, TNF-α, and IL-12)." (PMID 34901012, 2021). "While enhanced secretion of granulysin and granzyme B directly account for increased tumor lysis, IFN-γ and TNF-α stimulate the endogenous immune system and indirectly enhance anti-tumor activity." (PMID 33807875, 2021). "H&E staining revealed significant inflammatory cell infiltration and intramucosal tumor in the colon of the AOM/DSS group, and the mRNA levels of inflammatory cytokines (IL-1β, IL-6, and TNF-α) were significantly increased." (PMID 33708251, 2021). "The activation of TNF-α, IL-6, IL8, and VEGF triggers downstream signaling involved in promoting tumor growth and invasiveness to other parts of the body." (PMID 34096454, 2021).